CLIC1 (CLIC family member 1)
Diseases named in the same sentence as CLIC1 in open-access papers (continued):
Sharing a sentence is not in itself a finding about the gene and the disease.
cancer (continued). "Intriguingly, CLIC1 is constitutively active within cancer stem cells (CSCs), while it seems less relevant for the survival of non-CSC GBM subpopulations and for normal cells." (PMID 30918838, 2019). "On the contrary, in cancer cells the specific intracellular microenvironment generated by the high production of ROS and low pH levels enhances CLIC1 functional expression promoting its constitutive membrane localization as an active ion channel." (PMID 30918838, 2019). "In recent years, among the possible cancer-specific molecular targets for metformin, CLIC1 has been proposed to represent the main transducer of the biguanide effects in GSCs." (PMID 30918838, 2019). "Recent studies revealed that CLIC1 is expressed in various cancers, and plays crucial roles in multiple cell functions including control of the cell cycle, apoptosis, proliferation, invasiveness, and metastasis." (PMID 29796185, 2018). "Chloride intracellular channel 1 (CLIC1) has been shown to exhibit increased protein levels in several cancers including CRC." (PMID 30108113, 2018). "We also observed enhanced phosphorylation of ERK1/2 and NF-κB p65 subunit following CLIC1 overexpression, the activation of which has been shown to enhance motility in a range of cancers." (PMID 29462791, 2018). "All tested malignant tumors secreted CLIC1 and CLIC4 into the media and shedding was usually higher than from benign tumors." (PMID 30282979, 2018). "Immunohistochemistry showed that CLIC1 was present in the cytoplasm of carcinoma cells, and that the very strong or very weak expression of CLIC1 was an independent poor prognostic factor." (PMID 29796185, 2018). "This study aims to investigate the potent lead TCM candidates for CLIC1 protein inhibitors against cancer." (PMID 29147652, 2017). "CLIC1 is a potential prognostic marker for some malignant tumors, and elevated CLIC1 expression is correlated with poor prognosis." (PMID 27861612, 2016). "We also found a large number of genes functioning in the plasma membrane; four genes CHRNA3, CLIC1, KCTD1 and KCNMA1 were discovered in iron channel complex; except KCTD1, all others were associated with cancer." (PMID 26367387, 2015). "It was proposed that CLIC1 can be a novel potential prognostic factor, for which up-regulation is correlated with cancer development and metastasis." (PMID 26287160, 2015). "This study adds to the current realization on the involvement of CLIC1 in tumorigenesis and progression of human malignant tumors." (PMID 22578365, 2012). "In addition, CLIC1 has been widely confirmed to play a significant role in the progression and metastasis of various cancers." (PMID 41142627, 2025). "In addition to IAA94, CLIC1 is shown to be inhibited by metformin, a drug that effectively blocks cancer stem cell viability." (PMID 32116799, 2020). "This information is helpful in targeting CLIC1 for cancer therapy as well as a prognosis marker." (PMID 32116799, 2020). "The basis for the different effects of CLIC1 inhibition in distinct cancer cells is currently unclear; however, one of the mechanisms might be the diverse regulatory crosstalk between Ca2+ and ROS56." (PMID 31316050, 2019). "Many different types of cancer express CLIC1 at high levels." (PMID 31316050, 2019). "How the vesicular transfer of CLIC1 is modulated in cancer therapy is a future challenge." (PMID 30279961, 2018). "In ESCC tissues, the CLIC1 protein was mainly expressed in the cytoplasm of cancer cells." (PMID 29796185, 2018). "CLIC1 is also secreted in extracellular vesicles (EVs) by cancer cells and is detected in biological fluids, fostering the hypothesis that secreted CLIC1 protein may increase GBM growth." (PMID 30279961, 2018). "In addition, the observation that CLIC1 overexpression can activate ERK1/2 and NF-κB p65 raises the possibility that MCPyV ST targets CLIC1/CLIC4 to regulate the mitogenic signaling pathways that contribute to cancer metastasis." (PMID 29462791, 2018).
cancer (continued). "The expression of CLIC1 correlates with cell proliferation and apoptosis in several cancers." (PMID 29796185, 2018). "Therefore, CLIC1 is a potential prognostic marker and drug therapy target for diverse malignant tumors." (PMID 29147652, 2017). "However, further studies are needed to elucidate the role of CLIC1 in development and progression in cancer." (PMID 27825122, 2016). "What's more, CLIC1 contributes to the resistant to redox and chemotherapy drugs in cancer cells." (PMID 27825122, 2016). "CLIC1 is involved in invasion, cancer cell motility and development of chemoresistance." (PMID 22415234, 2012). "Recent studies have shown that CLIC1 is highly expressed in several human malignant tumors." (PMID 22578365, 2012). "Importantly, in endothelial cells and cancer models, Clic1 inhibitor, Indanyloxyacetic acid (IAA) has been shown to functionally inhibit Clic1 by preventing translocation to the transmembrane region, and Clic1 remains predominantly in the cytoplasmic compartment." (PMID 37604246, 2023). "CLIC1 exists as either soluble cytosolic protein or transmembrane isoform (tmCLIC1), assembled in multimeric ion channel conformation and its functional overexpression in cancer cells supports its possible pharmacological targeting as innovative therapeutic option." (PMID 35135603, 2022). "However, our data reveal that CLIC1 might play a critical role in apoptosis resistance, diminishing the large surges in the Ca2+ concentration and ROS levels, and suggest the possibility for targeting CLIC1 to control apoptosis in cancer cells." (PMID 31316050, 2019). "Therefore, CLIC1 is a key regulator of Ca2+ signaling in the control of cancer cell survival." (PMID 31316050, 2019). "Thus, CLIC1 is a key regulator of Ca2+ signaling in the control of cancer cell survival." (PMID 31316050, 2019). "Thus, a potential new a therapy could be really successful if retains the efficacy and the discrimination capability among healthy and cancer cells, provided by CLIC1 localization, and the ability to block tmCLIC1, as metformin, but acting at lower doses." (PMID 30918838, 2019). "IPA revealed that “Cancer” was one of the top-ranking diseases, and also that “Cell Morphology”, “Cellular Growth and Proliferation”, “Cellular Development”, “Cellular Movement”, and “Cellular Assembly and Organization” were top-ranking biological functions related to the depletion of CLIC1." (PMID 29796185, 2018). "CLIC1, a member of the CLIC protein family, has emerged as a pivotal player in cancer progression across various malignancies." (PMID 38027011, 2023). "The intracellular chloride channels CLIC1 and CLIC4 are promising cancer therapeutic targets because of their activities as ion channels and signal transducers in cell cycle progression and the malignant transformation of cancer cells." (PMID 37408210, 2023). "Nonetheless, two related CLICs, CLIC1 and CLIC4, are overexpressed in cancer stem cells and envisioned as novel therapeutic targets." (PMID 26191006, 2015). "At least two identified proteins (CLIC1 and PSME) have previously been proposed as potential biomarkers for cancer." (PMID 24422745, 2014). "For the first time, our paper describes EIF4A1, CLIC1, PRDX6, CLIC4, ENO1, ANXA4, EMD and Ku70 in relation to EEC, although their role is well established in other cancers." (PMID 22415234, 2012). "Chloride intracellular channels (CLIC1–6) are non-canonical self-assembling anion channels involved in physiological cell functions as well as in cancer development." (PMID 35135603, 2022). "In our previous study, we found that the radioresistant cancer cells are more tolerant than control cells to irradiation owing to the modulation of cellular antioxidant defense proteins such as Mn-SOD, PRDX2, and CLIC1." (PMID 25605256, 2015).
cancer (continued). "Moreover, CLIC1-silencing in cancer stem cells (CSCs) isolated from human GBM patients negatively influences proliferative capacity and self-renewal properties in vitro and impairs the in vivo tumorigenic potential." (PMID 26429879, 2015).
infection (5 papers, 2014 to 2025). The state of being infected such as from the introduction of a foreign agent such as serum, vaccine, antigenic substance or organism. "The results of the RT-PCR assay revealed that the expression of CLIC1 in the shCLIC1 group was significantly downregulated compared with the control group, indicating effective infection with AAVs." (PMID 39953602, 2025). "We knocked-down CLIC1 expression in CSCs by specific shRNA lentiviral infection (shCLIC1), verified by immunocytofluorescence and Western blot." (PMID 25361004, 2014). "Considering the properties of CLIC1, it is reasonable to think that it is involved in monocyte proliferation, infiltration into the brain parenchyma through the blood brain barrier, acquisition of macrophage characteristics and migration to the infection site." (PMID 32098256, 2020). "PPARα/RXRα activation, Wnt/β-catenin signaling, GNRH signaling cAMP-mediated signaling, and ERK/MAPK signaling are the most prominent among the signaling pathways significantly affected by PR8 infection but were not impacted by the infection in CLIC1 KD cells." (PMID 38257829, 2024).
benign tumors (1 paper, 2018). "Normal ovaries and benign tumors did not typically stain for CLIC1." (PMID 30282979, 2018). "Analysis of CA125 staining showed that, like CLIC1, CA125 was usually not detected in normal ovaries or benign tumors, whereas epithelial cells of the fallopian tubes stained weakly." (PMID 30282979, 2018).
cardiovascular disorder (1 paper, 2016). A disease involving the cardiovascular system. "In addition, the inhibitory effects on adhesion molecules may offer a potential application of CLIC1 inhibition for the treatment of cardiovascular disorders, such as AS." (PMID 27861612, 2016).
central nervous system disorder (1 paper, 2025). A disease involving the central nervous system. "All these findings suggest that CLIC1 is a critical therapeutic target for central nervous system disorders and holds promising potential for treating CIRI." (PMID 40966238, 2025).
neurological disorders (1 paper, 2025). "Chloride intracellular channel 1 (CLIC1) and the nuclear factor erythroid-related factor 2 (Nrf2)/heme oxygenase-1 (HO-1) pathway have been implicated in many neurological disorders." (PMID 40966238, 2025).
CLIC1 also shares sentences with these, for which no sentence is quoted: pancreatic ductal adenocarcinoma (3 papers); nasopharyngeal carcinoma (2); acute kidney injury (1); adenoma (1); Anxiety (1); autism (1); autism spectrum disorder (1); benign ovarian tumors (1); cardioembolic stroke (1); cervical cancer (1); channelopathies (1); digestive system neoplasm (1); esophageal cancer (1); Jaundice (1); liver disease (1); malignant renal tumors (1); mastitis (1); Menkes disease (1); neurodegenerative disease (1); oral squamous cell carcinoma (1); osteoarthritis (1); post-traumatic stress disorder (1); prostate tumor (1); psoriatic arthritis (1); pulmonary arterial hypertension (1); renal cell carcinoma (1); schizophrenia (1); Stroke (1); type 1 diabetes (1).